HSPB2 (heat shock protein family B (small) member 2)
Description:
May regulate the kinase DMPK.
Synonyms: MKBP; Hs.78846; HSP27; LOH11CR1K
Tractability: No criterion of Open Targets' tractability assessment is met for any kind of drug.
Gene: Protein-coding gene on chromosome 11 (111,912,159 to 111,914,093, forward strand). Ensembl gene ENSG00000170276.
Subcellular location: Cytoplasm; Nucleus
Subcellular location (Human Protein Atlas): Golgi apparatus; Nucleoplasm
Pathways (Reactome):
Cellular responses to stimuli: Attenuation phase; HSF1 activation; HSF1-dependent transactivation; Regulation of HSF1-mediated heat shock response
Gene Ontology:
Molecular function: protein binding; enzyme activator activity; structural constituent of eye lens
Biological process: negative regulation of apoptotic process; protein refolding; response to heat; response to unfolded protein
Cellular component: cytoplasm; nucleoplasm; nucleus; cytosol
Genetic constraint (gnomAD): Loss-of-function variants: 15 observed, 14.49 expected, observed/expected ratio (o/e) 1.04, 90% interval 0.69 to 1.58. The upper end of that interval is the gene's LOEUF score, 1.58, which puts it in group 6 of 6, group 1 being the genes least tolerant of losing a copy. Missense variants: 242 observed, 244.39 expected, observed/expected ratio (o/e) 0.99, 90% interval 0.89 to 1.1. Synonymous variants: 110 observed, 107.28 expected, observed/expected ratio (o/e) 1.03, 90% interval 0.88 to 1.2.
Homologues: Orthologues: chimpanzee HSPB2 (100% identical), macaque HSPB2 (100% identical), guinea pig HSPB2 (99% identical), rabbit HSPB2 (98% identical), mouse Hspb2 (97% identical), dog HSPB2 (96% identical), tropical clawed frog hspb2 (54% identical), zebrafish hspb2 (47% identical), Drosophila melanogaster l(2)efl (32% identical), Drosophila melanogaster Hsp67Ba (27% identical), Drosophila melanogaster Hsp67Bc (26% identical), Drosophila melanogaster Hsp23 (25% identical), and 12 more. Paralogues in human: HSPB1 (36% identical), CRYAB (35% identical), HSPB6 (33% identical), CRYAA (31% identical), HSPB3 (25% identical), HSPB8 (25% identical), HSPB7 (22% identical), HSPB9 (12% identical).
Diseases named in the same sentence as HSPB2 in open-access papers:
HSPB2 is named in the same sentence as 45 diseases in open-access papers, as found by Europe PMC text mining. Sharing a sentence is not in itself a finding about the gene and the disease. The quoted sentences say what the papers report.
breast carcinoma (7 papers, 2016 to 2023). "In conclusion, high HSPB2 mRNA expression levels are associated with breast cancer patients’ relapse and poor survival." (PMID 36077156, 2022). "The expression of HspB1, HspB2, and HspB5 is reported to be associated with resistance to apoptosis in human breast cancer cells and oral verrucous carcinoma." (PMID 32927696, 2020). "The study has pointed out that HSPB2 is highly expressed in human breast cancer cells and is related to apoptosis resistance." (PMID 35154459, 2022). "HSPB2 also inhibits the apoptotic pathway by being concentratedly expressed in breast cancer and inhibiting the activation of caspase-8 in breast cancer." (PMID 35154459, 2022). "In this study, we investigated the potential prognostic significance of HSPB2 mRNA expression levels in breast cancer, which represents the most frequent malignancy in females and one of the three most common cancer types worldwide." (PMID 36077156, 2022). "Although it is mainly expressed in cardiac and skeletal muscle, the HSPB2 gene was also reported to be expressed in human breast cancer cell lines and constitutes an inhibitor of apical caspase activation in the extrinsic apoptotic pathway." (PMID 36077156, 2022). "The initial comparison of HSPB2 mRNA levels among 16 pairs of malignant breast tumors and their adjacent non-cancerous breast tissues revealed the downregulation of the HSPB2 mRNA expression in the majority of malignant breast tumors (p < 0.001)." (PMID 36077156, 2022). "Notably, high HSPB2 mRNA expression predicts poor disease-free survival and overall survival of breast cancer patients." (PMID 36077156, 2022). "Overexpression of HspB1, HspB2, and HspB5 inhibits apoptosis in breast cancer cells." (PMID 32927696, 2020). "Heat shock protein family B member 2 (HSPB2) is a member of the sHSPs, which is found to be expressed, among others, in human breast cancer cell lines and constitutes an inhibitor of apical caspase activation in the extrinsic apoptotic pathway." (PMID 36077156, 2022). "Another interesting observation from the present study is that several HSPs were downregulated in all breast cancer subtypes: DNAJB4, DNAJC18, HSPA12A, HSPA12B, HSPB2, HSPB6, and HSPB7." (PMID 29954368, 2018). "Multivariate Cox regression analysis revealed that HSPB2 mRNA overexpression is a significant predictor of poor prognosis in breast cancer, independent of other clinicopathological factors." (PMID 36077156, 2022). "Despite the fact that many sHSPs are overexpressed in a wide range of solid tumors, we observed that HSPB2 gene transcription is predominantly downregulated in malignant breast tumors compared to their adjacent non-cancerous breast tissues." (PMID 36077156, 2022).
pancreatic cancer (4 papers, 2021 to 2025). "Other studies support the downregulation of HSPB2 in cancer, as well; specifically, HSPB2 mRNA was lower in esophageal squamous cell carcinoma cell lines, due to hypermethylation of the promoter of the HSPB2 gene, while HSPB2 mRNA was also found to be barely expressed in pancreatic cancer." (PMID 36077156, 2022). "Low-molecular-weight heat shock proteins (lmHSPs), including HSP27, HSPB2, HSPB6, and αA-crystallin, play a complex role in the biology of pancreatic cancer by exhibiting both pro- and anti-tumorigenic effects." (PMID 41148842, 2025).
Alzheimer disease (3 papers, 2012 to 2021). A progressive, neurodegenerative disease characterized by loss of function and death of nerve cells in several areas of the brain leading to loss of cognitive function such as memory and language. "The extracellular presence of HspB2 has been reported in the senile plaques of Alzheimer disease and in cerebral amyloid angiopathy." (PMID 22272249, 2012). "HspB2 has also been found in the senile plaques of Alzheimer disease." (PMID 22272249, 2012).
cardiomyopathy (3 papers, 2014 to 2020). A disease of the heart muscle or myocardium proper. "While the αB-crystallin/HspB2 double knockout (due to overlapping exons), has increased stress induced cardiomyopathy with ischemia-reperfusion injury and myocardial pressure overload, the phenotype is not seen with a functional HspB2 knockout, reinforcing αB-crystallin’s importance." (PMID 32581848, 2020). "From the clientele and phenotypes identified herein, it is tempting to speculate that small molecule activators of HspB2 might be deployed to mitigate mitochondrial related diseases such as cardiomyopathy and neurodegenerative disease." (PMID 26465331, 2015).
cardiac hypertrophy (2 papers, 2015 to 2016). "In a subsequent study the authors found that animals harboring a cardiac-specific HspB2 genetic deletion had an equal propensity for ischemia induced cardiac hypertrophy suggesting that αB-crystallin and HspB2 have at least partly redundant activities in the heart." (PMID 27330996, 2016).
cerebral amyloid angiopathy (2 papers, 2012 to 2018). "In addition, HspB2/B3 co-localizes with amyloid β deposits in vessels in cerebral amyloid angiopathy." (PMID 29969581, 2018). "The low-activity chaperones HspB2, HspB6 and HspB8 specifically associate with fibrillar amyloid β rather than non-aggregated forms in a hereditary cerebral amyloid angiopathy caused by the rapidly aggregating amyloid β1–40 carrying the “Dutch” mutation 22Glu → Gln." (PMID 29969581, 2018).
colorectal cancer (2 papers, 2020 to 2022). A primary or metastatic malignant neoplasm that affects the colon or rectum. "It was confirmed for the first time that miR-17-5p directly targets and reduces the expression level of HSPB2 and plays an oncogenic miRNA role in the pathogenesis of colorectal cancer by regulating HSPB2." (PMID 35154459, 2022). "Similarly, colorectal cancer patients with high expression of CRIP2, PRAM1, HSPB2 or CERCAM had poorer OS comparing with low expressed groups (logrank = 0.0073, 0.0053, 0.0036 and 0.0023, respectively)." (PMID 33125346, 2020). "However, whether HSPB2 is also involved in regulating the development of colorectal cancer is not yet clear." (PMID 35154459, 2022).
Glucose intolerance (2 papers, 2016 to 2023). Glucose intolerance (GI) can be defined as dysglycemia that comprises both prediabetes and diabetes. "It has been experimentally shown that HspB2 deficiency possesses a protective effect form diet-induced glucose intolerance." (PMID 37569434, 2023). "The outcome revealed that αB-crystallin/HspB2 has a role in the development of glucose intolerance, likely by increasing insulin resistance." (PMID 27330996, 2016).
ischemia (2 papers, 2012 to 2022). A hypoperfusion of the BLOOD through an organ or tissue caused by a PATHOLOGIC CONSTRICTION or obstruction of its BLOOD VESSELS, or an absence of BLOOD CIRCULATION. "High expression of HSPB2 in heart has protective roles on some heart diseases such as cardiac hypertrophy and ischemia." (PMID 35928554, 2022). "HspB2 is also known to protect myocardium from ischemia and help in recovering from ischemic stress during reperfusion." (PMID 22272249, 2012). "Studies on isolated hearts of HspB2 knockout mice showed impaired systolic function and were found to be inefficient in regenerating vital molecules such as ATP and phosphocreatine during reperfusion after ischemia." (PMID 22272249, 2012).
Senile plaques (2 papers, 2012 to 2015). Senile plaques are extracellular deposits of amyloid in the gray matter of the brain. "In addition, HspB2 has recently been found in the senile plaques of AD." (PMID 26465331, 2015).
bladder tumors (1 paper, 2023). "The noted downregulation of HSPB2 and HSPB3 mRNA expression levels in bladder tumors urged us to examine their potential association with the clinicopathological features of BlCa." (PMID 36768927, 2023). "A significant downregulation of the HSPB2 and HSPB3 genes expression was observed in bladder tumors as compared to matched normal urothelium; yet, increased HSPB2 and HSPB3 levels were noted in muscle-invasive (T2–T4) vs. superficial tumors (TaT1), as well as in high-grade vs. low-grade tumors." (PMID 36768927, 2023). "Thus, HSPB2 and HSPB3 expression in bladder tumors and cell lines was assessed and their potential clinical significance concerning patients’ survival and disease outcome." (PMID 36768927, 2023). "Therefore, we then evaluated the clinical significance of the HSPB2 and HSPB3 genes expression levels in bladder tumor samples and matched adjusted normal bladder specimens." (PMID 36768927, 2023). "Given that the involvement of HSPB2 and HSPB3 genes in bladder tumorigenesis remains unclear, we herein analyze HSPB2 and HSPB3 gene expression levels in bladder tumors and matched adjacent normal urothelium." (PMID 36768927, 2023). "Total RNA from 100 bladder tumor samples and 49 paired non-cancerous bladder specimens were isolated, and an accurate SYBR-Green based real-time quantitative polymerase chain reaction (qPCR) protocol was developed to quantify HSPB2 and HSPB3 mRNA levels in the two cohorts of specimens." (PMID 36768927, 2023).
breast tumors (1 paper, 2022). "The significant downregulation of HSPB2 gene expression was revealed in breast tumors compared to their adjacent non-cancerous breast tissues." (PMID 36077156, 2022).
cognitive decline (1 paper, 2025). "In contrast, Rapid Decline showed increased β-amyloid (bA), glial and inflammatory markers (CD44, PLXNB1), and stress- and mitochondrial-related proteins (GSTP1, AK4, HSPB2, FBXO2, IGFBP5), which have been associated with neurodegeneration and cognitive decline in AD." (PMID 40799531, 2025).
colon cancer (1 paper, 2022). "In addition, it has recently been hypothesized that the inhibition of HSPB2 by miR-17-5p promotes cell proliferation, migration, and invasion of colon cancer cell lines." (PMID 36077156, 2022).
dementia (1 paper, 2023). Loss of intellectual abilities interfering with an individual's social and occupational functions. "Additionally, HSPB2 elevation has also been observed in aging and dementia, which is considered a resistance mechanism against protein aggregation." (PMID 37606039, 2023).
diabetes (1 paper, 2016). "To evaluate the functional role of αB-crystallin/HspB2 in diet-induced obesity and diabetes, we placed αB-crystallin/HspB2-deficient and littermate controls (wild-type, WT) on normal chow or high fat diets and monitored weight and metabolic parameters over time." (PMID 27330996, 2016).
glioma (1 paper, 2019). A benign or malignant brain and spinal cord tumor that arises from glial cells (astrocytes, oligodendrocytes, ependymal cells). "The single CpG methylation and HSPB2 expression differed regarding the G-CIMP status (or IDH mutations), but they were not significantly altered in GBMs or in IDH mutant gliomas compared to nontumor brains." (PMID 31088577, 2019). "The DNA methylation status and gene expression of HSPB2 were not significantly altered between nontumor brains and non-G-CIMP/IDHwt gliomas of each grade, indicating that it is not a good candidate for diagnostic use." (PMID 31088577, 2019).
Insulin resistance (1 paper, 2016). Increased resistance towards insulin, that is, diminished effectiveness of insulin in reducing blood glucose levels. "We have demonstrated that genetic ablation of αB-crystallin/HspB2 results in improved glucose tolerance and diminished insulin resistance in mice maintained on a high fat diet." (PMID 27330996, 2016). "Taken together, we provide evidence that genetic KO of αB-crystallin/HspB2 leads to less insulin resistance while mice are on a high fat diet." (PMID 27330996, 2016). "Collectively, these data reveal that αB-crystallin/HspB2 plays a role in development of insulin resistance during a high fat diet challenge." (PMID 27330996, 2016). "Our transcript profiling provides a foundation to begin to decipher the molecular mechanisms by which αB-crystallin and/or HspB2 mediates insulin resistance." (PMID 27330996, 2016). "Taken together, these data reveal that αB-crystallin/HspB2 is involved in the genesis of insulin resistance on a high fat diet, and we provide extensive RNA profiling to illuminate potential mechanistic insights into the muscle-specific role of αB-crystallin/HspB2." (PMID 27330996, 2016). "Our data suggest that αB-crystallin/HspB2 may contribute to insulin resistance through its role in skeletal muscle." (PMID 27330996, 2016). "As cytokine signaling induces cellular stress and αB-crystallin/HspB2 both contribute to this response, αB-crystallin/HspB2 may directly link inflammation and insulin resistance." (PMID 27330996, 2016). "Cumulatively, these data suggest that αB-crystallin/HspB2 KO mice on a high fat diet have improved glucose tolerance, which may be a result of diminished insulin resistance." (PMID 27330996, 2016). "αB-crystallin and HspB2 are highly expressed in skeletal muscle, a likely tissue where αB-crystallin/HspB2 activity may affect insulin resistance, especially considering αB-crystallin is upregulated in muscle in rodents and humans in the setting of insulin resistance." (PMID 27330996, 2016).
memory impairment (1 paper, 2023). "In contrast, the difference between the TG-TBI and TG-sham groups was less pronounced, indicating that HSPB2 overexpression mitigated spatial learning and memory impairment following TBI." (PMID 37606039, 2023).
muscular disease (1 paper, 2015). Myopathy is a peripheral nervous system disease consisting of any abnormal condition or disease of the muscular tissues; commonly designates a disorder involving skeletal muscle. "The systems biology analysis herein, however, posits HspB2 as a player in neurodegenerative, mitochondrial, and muscular disease." (PMID 26465331, 2015). "Although many other sHSPs (including HspB5) have been found to play a role in various diseases including neurodegenerative and muscular disease, disease-associated alleles of HspB2 have not been identified." (PMID 26465331, 2015).
myocardial ischemia (1 paper, 2016). A disorder of cardiac function caused by insufficient blood flow to the muscle tissue of the heart. "However, deficiency of αB-crystallin and HspB2 has been observed to result in protection from myocardial ischemia in some studies, which was also unexpected per these authors, and was suggested to be from altered mitochondrial metabolism." (PMID 27330996, 2016).
myopia (1 paper, 2017). "Such expression changes were evident, particularly in the late myopia dataset where a wide range of genes linked with oxidative stress were either up-regulated (GPX1, GSTA3, MT-4, APOA1, OTUB, PTGDS, HSPB1, HSPB2) or down-regulated (XHD, SLC40A1, TF, SOD3, HPGDS, BCMO1)." (PMID 28852117, 2017).
myotonic dystrophy (1 paper, 2022). An inherited progressive disorder affecting the muscles. "Indeed, HSPB2 has been observed upregulated in myotonic dystrophy patients." (PMID 35281256, 2022). "The MKBP name was given since HSPB2 was described as an interactor and activator of DMPK, a kinase that physiologically acts in muscle structure maintenance and can be deregulated in myotonic dystrophy." (PMID 35281256, 2022).
neuropathies (1 paper, 2019). "Despite not being a member of the HSP70 family, the small HSPB2 chaperone was recently shown to be associated with neuropathies when disregulated and thus may play a role in neuron proliferation, a process shown to be important for acclimation." (PMID 31850067, 2019).
Obesity (1 paper, 2016). Accumulation of substantial excess body fat. "Taken together, these data led us to investigate if αB-crystallin/HspB2 may have a role in obesity-related metabolic disorders." (PMID 27330996, 2016). "As αB-crystallin and HspB2 are molecular chaperones and data suggests their expression is elevated in the skeletal muscle of diabetic and obese animals, we sought to determine if αB-crystallin and HspB2 collectively play a functional role in the metabolic phenotype of diet-induced obesity." (PMID 27330996, 2016).
stomach adenocarcinoma (1 paper, 2019). "In the stomach adenocarcinoma dataset, strong positive correlations in gene expression were identified between members of the small HSP family, including HSPB2, HSPB5 (CRYAB), HSPB6, HSPB7 and HSPB8, as well as the HSP40 family member DNAJB5, with superoxide dismutase (SOD3)." (PMID 30578123, 2019).
Stroke (1 paper, 2023). Sudden impairment of blood flow to a part of the brain due to occlusion or rupture of an artery to the brain. "The OGD/r model is also commonly used to simulate ischemic neuronal injury in stroke, suggesting that elevation of HSPB2 level is a universal phenomenon in acute neuronal injury." (PMID 37606039, 2023). "The increase in HSPB2 expression in primary neuron cultures subjected to OGD/r suggested its involvement in acute neuronal injuries beyond TBI, including stroke and other acute CNS injuries." (PMID 37606039, 2023).